IL10 (interleukin 10)
Diseases named in the same sentence as IL10 in open-access papers (continued):
Sharing a sentence is not in itself a finding about the gene and the disease.
infection (continued). "WT and IL-10−/− mice exhibited elevated serum ALT on day 4 and 5 after infection, with serum values in the IL-10−/− mice higher than WT on day 5 post infection, though these differences did not attain statistical significance." (PMID 22880122, 2012). "Elevated levels of pro-inflammatory cytokines IFN-γ and TNF-α were found at day 5.5 of infection in Il10−/− mice." (PMID 22876184, 2012). "In the initial stages of infection, BP-induced vigorous immune responses in both cell types, while BM-induced an anti-inflammatory response (i.e., IL-10) in the early stages of infection then transitioned into a traditional immune response." (PMID 23293773, 2012). "Analyses show that liver leukocytes from uninfected tiger mice marginally expressed IL-10/GFP, whereas after infection, 10%±1% of the gated leukocytes were IL-10/GFP+." (PMID 22880122, 2012). "Our observation of elevated levels of IL-10 in cord blood plasma of the infants of infected mothers and in cord blood plasma of infected children provides a potential mechanism by which maternal infections may subsequently increase susceptibility to infection in children." (PMID 22848773, 2012). "We found that MCMV-infected Il10−/− mice exhibited reduced virus loads already during acute infection." (PMID 22876184, 2012). "IL-10 protein levels were slightly increased on day 3, but peaked significantly at day 4 after infection." (PMID 22880122, 2012). "During an overwhelming infection, as in our mouse studies, the anti-inflammatory effects of IL-10 are most likely beneficial to the host by down-regulating inflammation and its unfavourable effects." (PMID 22347396, 2012). "Recently, downregulation of let-7 family members was identified as control major regulators of inflammation, including IL-6 and IL-10 in macrophages and HeLa cells upon infection with Salmonella." (PMID 22312311, 2012). "To check the biological relevance of these results, we analyzed the data of IL10 production following infection with influenza virus." (PMID 22768144, 2012). "This is in contrast to previous reports that found IL-10 mediated regulation of the immune response by NK cells after systemic or local infection in mice and in human using in vitro methods." (PMID 23077546, 2012). "The analysis of CD8+ T-cells in the peripheral blood revealed that most of the IFNγ+ cells were CD8+IFNγ+IL-10+ in the acute and in the chronic infection and accumulated in blood in the chronic phase of infection." (PMID 22532799, 2012). "The authors observed upregulation of TLR2 and TLR4 from day 1 to day 28 postinfection, and increased expression correlated with higher mRNA levels for TNFα, IL-17, IL-10, and TGFβ during early infection." (PMID 22523644, 2012). "Here we show that schistosome-specific antibody-secreting B cells accumulate in the liver as the infection progresses to the chronic state and that this accumulation is dependent on the cytokine Interleukin-10." (PMID 22291593, 2012). "IL-10 message is induced during experimental infection with a number of mycobacterial species, and has been correlated with enhanced disease in TB patients." (PMID 23239994, 2012). "The presence IL-10 secreting cells, with a regulatory phenotype, may have modulated potentially harmful effects associated with the development of a Th1-immune response, leading to the control of pathology at the infection site of mice immunized with nucleossomal histones." (PMID 23284976, 2012). "In our study, we have found an increase of spleen CD4+ T lymphocytes producing IL-10 seven days after infection, in addition to the IFNγ and TNF-α producing cells." (PMID 22666132, 2012). "In this ex vivo protocol the kinetics of IFN-γ parallels those of GM-CSF and IL-10 production, displaying an early rise by the 3rd or 4th day after infection, reaching peak levels between days six and ten, and then declining sharply." (PMID 22500859, 2012).
infection (continued). "Adaptive type 1 regulatory (Tr1) CD4+ cells, which do not express CD25, FoxP3 or CD127 on their surface, have recently been identified as the main source of IL-10 in experimental murine infection with P. yoelii." (PMID 22973442, 2012). "And had an inflammatory profile on the seventh day after infection to be held the balance between cytokines TNF-α/IL-10." (PMID 22412949, 2012). "The high levels of serum IL-10 and IL-13 in the patient with fatal HME compared to non fatal HME is consistent with our murine data where IL-10 peaks in the serum at later stages of lethal infection, which occurs before animals succumb to infection." (PMID 22607204, 2012). "Similar to this finding, infection of THP-1 macrophages with a recombinant M.smegmatis strain expressing PPE18 led to TLR2 dependent induction of IL-10." (PMID 23284742, 2012). "In fact, an approximate one-week delay in the transcription ratio for CD3, TNF-α, IFN-γ, iNOS, IL-10 and arginase I was observed in IL-12p40KO mice at the third and fourth weeks after infection." (PMID 23152844, 2012). "IL-10 levels remained lower after the second day of infection with RUH875 and RUH134 as compared to LUH5875." (PMID 22347396, 2012). "From experimental studies increases in IFNγ secreting cells and interleukin 10 have been shown as early as 7 and 10 days post infection, respectively." (PMID 22439879, 2012). "It is well established that IL-4 exacerbates leishmaniasis when added exogenously, and IL-10 mutant mice become resistant to infection." (PMID 22448168, 2012). "Elevated IL-10 characterizes chronic stages of schistosome infection and is produced by B cells starting from week 12 during infection." (PMID 22347409, 2012). "While one shows that IL-10 prevents immunopathology and lethal disease, the other indicates that IL-10 has little impact on sublethal infection but inhibits beneficial Th17 responses during high-dose challenge." (PMID 22393401, 2012). "On day 4 post infection, both WT and IL-10−/− livers had comparable reductions in PAS staining and an increased presence of inflammatory foci (data not shown)." (PMID 22880122, 2012). "Children with asymptomatic P. falciparum infections have elevated plasma IFN-γ, TNF and IL-4 levels, whilst a cross-sectional study of third trimester pregnancies reported increased G-CSF and IL-10 in women with asymptomatic infections." (PMID 23155405, 2012). "According to these results, Lr1505 treatment would beneficially regulate the balance between pro-inflammatory mediators and IL-10, allowing an effective inflammatory response against infection and avoiding tissue damage." (PMID 22989047, 2012). "The results shows that the frequency of IFN-γ+ and TNF-α+ CD8+ T cells on day 5 post infection were comparable between WT and IL-10−/− mice." (PMID 22880122, 2012). "IL-10 is an important anti-inflammatory cytokine produced by macrophages during infection that strongly inhibits IL-12 and NOS2 expression." (PMID 22829768, 2012). "Here we demonstrate that infection of BALB/c mice with respiratory syncytial virus (RSV) induced IL-10 production by CD4+ and CD8+ T cells in the airways at later time points (e.g. day 8); a proportion of these cells also co-produced IFN-γ." (PMID 22393401, 2012). "Analysis of IL-10 production indicated that stimulation with a MOI of 200 (multiplicity of infection of MDDCs—H." (PMID 22526791, 2012). "Simulations suggested that the local IL10 expression, higher in the dual compared to the single infection, was a bystander effect induced by the type three secretion system (TTSS) of B. bronchiseptica through Treg cells." (PMID 22253585, 2012). "Although T-bet and CD127 expression were not directly addressed, Foxp3− ‘effector’ CD4+ T cells also appear to be the major CD4+ T cell subset producing IL-10 during infection of mice with L. major." (PMID 22911108, 2012).
infection (continued). "Inflammatory and immunologic responses, mediated by increased levels of TH1-type (TNF-α and IFN-γ) and TH2-type cytokines (IL-10 and IL-6), appear to be important for recovery from infection." (PMID 21912565, 2012). "Morbidity and mortality were associated with the severity of lung pathology and a specific immune response characterized by low levels of anti-inflammatory (IL-10) and specific pro-inflammatory (IL-12p40 and IL-23) cytokines at the first day of infection." (PMID 22347396, 2012). "Alternatively, and very interestingly, BM stimulated minimal cytokine secretion from macrophages and ATII cells in the initial infection stage but stimulated the secretion of pro-inflammatory suppressor, IL-10." (PMID 23293773, 2012). "How sex-related IL10 production influences the outcome of infection and/or the amplitude of humoral immune response in the two sexes has not been investigated." (PMID 22768144, 2012). "IL-10 increment is more gradual with low levels recorded at the start of infection and then gradually increased towards the later stages of infection." (PMID 23323093, 2012). "Imipramine caused strong suppression of IL-10 and TGF-β production that correlated with successful resolution of infection." (PMID 23301108, 2012). "IL-10 was detectable at 4 hours after infection and maximal production occurred at 24 h after infection." (PMID 22470519, 2012). "Macrophages and dendritic cells, B cells and CD4+ T cells have been shown to produce IL-10 during this infection, though their contributions to IL-10 production in acutely infected livers remain to be examined." (PMID 22880122, 2012). "The numbers of infiltrating leukocytes in IL-10−/− mice were increased on days 5 and 7 after infection compared to WT, implying IL-10 regulates the magnitude of leukocyte infiltration." (PMID 22880122, 2012). "Though levels of these cytokines declined after 4 days post infection in WT and IL-10−/− mice, they remained elevated in IL-10−/− mice over those in WT mice at most time points analyzed." (PMID 22880122, 2012). "IL-10, one of inhibitory cytokines, generally deactivates macrophages and permits enhanced bacterial intracellular growth during infection." (PMID 22470519, 2012). "As the infection proceeded, and consistent with our empirical work, IFNγ and IL10 expression rapidly peaked and then slowly decreased below the threshold through the course of the infection." (PMID 22253585, 2012). "We also looked for effects of maternal infection on induction of immune tolerance by measuring levels of IL-10 in newborn plasma." (PMID 22848773, 2012). "IL-10 is an anti-inflammatory cytokine that regulates the extent of host immunity to infection by exerting suppressive effects on different cell types." (PMID 22876184, 2012). "Although all the viruses’ infection decreased the production of IL-10, a lower level was observed in V K627 and rTsE627K groups than that in rVK627E and TsE627 groups." (PMID 22719870, 2012). "At day 2 post-infection, we observed an 84% higher proportion of IL-10-producing splenic CD4+ T cells from rD7-immunized mice compared to splenocytes of mock-immunized mice (p = 0.016)." (PMID 23236530, 2012). "We also observed a tendency to increase IL-10 levels in patients with HPV occurred simultaneously with other infections." (PMID 22550593, 2012). "In parallel, genes involved in the IL10 pathway (micro-arrays) as well as IL10 itself (QPCR) were significantly up-regulated by the infection." (PMID 22720048, 2012). "While virus titers in the salivary gland and lungs were comparable with B6 mice at day 7 post infection (p.i.), they were considerably diminished at day 14 and 21 p.i. in Il10−/− mice." (PMID 22876184, 2012). "TNF-α and IL-10 expression were also significantly elevated in PBMCs isolated from calves on day 4 post-BHV-1 infection but these responses were similar when comparing WMS and PA calves." (PMID 22435642, 2012).
infection (continued). "At the first day of infection, levels of IL-10 in lungs were significantly (p<0.05) lower in mice infected with RUH875 and RUH134 as compared to infection with LUH5875 and LUH8326." (PMID 22347396, 2012). "The production of IFN-γ and CXCL9 by WT and IL-10−/− liver leukocytes was increased as infection progressed." (PMID 22880122, 2012). "It is possible that IFN-γ and IL-10 are produced at the sites of infection, as observed in leishmaniasis, as a result of local recruitment and accumulation of activated CD4+ T cells in the perivascular area adjacent to infected ECs." (PMID 21912565, 2012). "Monocytes have also the capacity of a net inhibitory effect on NK cell activation through the release of IL-10 after an infection with M. tuberculosis and a depletion of these monocytes will increase the secretion of IFN-γ by NK cells." (PMID 23316194, 2012). "Taken together, these data establish that IL-10 differentially affects T cell populations during the acute phase of infection; while it profoundly inhibits virus-specific CD4 T cell response it has only a minor impact on MCMV-specific CD8 T cell responses." (PMID 22876184, 2012). "Production of IL-4 and IL-10 was statistically significant in infected animals at day 2 post-infection compared to their secretion preinfection (P < 0.05)." (PMID 22340040, 2012). "Another model in which IL-10 production is important in mediating resistance is an infection induced model of IBD, in which a lethal inflammatory response persists in the ileum after per oral administration of high dose T. gondii." (PMID 22479310, 2012). "Expression was significantly increased for 7 out of 78 putative genes of the IL-10 Signalling pathway present on the microarray following infection." (PMID 23046560, 2012). "In contrast, the modes of participation of other mediator molecules, such as prostaglandins and IL-10, in the manifestation of immunosuppressive activity of infection-induced suppressor macrophages diverse vary among pathogens." (PMID 22666284, 2012). "In L. donovani-infected BALB/c mice, the number of splenic CD4+ CD127dimCD25+GITR+ T cells expressing higher Foxp3 and IL-10 increased at 21 days of infection." (PMID 22928057, 2012). "Virus-specific CD8+ T cells have been identified as important IL-10 producers during infections of influenza A, respiratory syncytial virus and coronavirus." (PMID 22880122, 2012). "After systemic infection with L. donovani, a relatively silent phase during the first ∼3 weeks of infection was followed by increased expression of IL-4, IL-10, IL-13, and IL-21." (PMID 22275864, 2012). "In pathogenic species of Yersinia for example, the secreted V antigen protein induces IL-10 in macrophages to evade the host's inflammatory response during infection." (PMID 22558240, 2012). "Splenic IL-10-producing B cells were isolated from B. microti-infected mice and transferred into recipient mice (termed Breg recipients) on days -1 relative to infection with B. microti." (PMID 23071588, 2012). "NK cells are identified as prominent expressers of IL-10, although other cell populations also contribute to IL-10 in the liver during this infection." (PMID 22880122, 2012). "The CSF IL-10 concentration was significantly increased over control in both early and late infection stages and also increased with progression from early to late stage." (PMID 23145191, 2012). "The inflammatory response in the liver showed a similar picture with a significant increase of TNFα and IL10 under infection." (PMID 22815907, 2012). "These varied outcomes not only imply the central role of IL-10 in regulating the magnitude of immune responses, but also underscore the necessity for detailed studies of how IL-10 regulates immunity to infection for the benefit or detriment of the host." (PMID 22880122, 2012).
infection (continued). "In this study the plasma levels of three proinflammatory (TNF-α, IFN-γ, IL-4) and one anti-inflammatory cytokine (IL-10) during a primary infection with Mycoplasma mycoides subsp." (PMID 22533922, 2012). "We found a down-regulation of mRNA expression of HO-1 in renal tissue, as well as a decrease of plasma level of indirect bilirubin, a product of catabolism of toxic heme, TGF-β and IL-10 when compare with respective controls on day 0 after infection." (PMID 22952850, 2012). "For CD163, IL-10 inducing strains were able to keep the proportions of double positive SLAII/CD163 cells compared to mock-inoculated culture cells while infection with a IL-10-/TNF- strain (3267) produced a clear decline of double positive SLAII/CD163 cells." (PMID 21314968, 2011). "Based on the important roles contributed to these cytokines, we investigated the levels of IFN-γ, IL-12 (p40), (Th1 cytokines) and IL-4, IL-10 (Th2 cytokines) after 3 months of infection." (PMID 22206029, 2011). "In contrast, infection with the human apathogenic TCRV was associated with high levels of IL-6, IL-10 and TNF-α." (PMID 21572983, 2011). "To confirm this observation, we quantified IL-10 levels in MDM supernatants following their infection with T. gondii." (PMID 21526166, 2011). "While IL-4 mRNA expression was similar in wt and Mif−/− mice at 9 days post infection, IL-10 mRNA expression and protein in ileal mucosa were reduced in Mif−/− compared to wt mice (data not shown)." (PMID 21977228, 2011). "The effects of pro-inflammatory cytokines are counterbalanced by down-regulatory cytokines such as interleukin-10 (IL-10) which is produced by the activated macrophages, monocytes, Th2, and T regs, in response to infection." (PMID 22140472, 2011). "We identified extracellular GAPDH as the GBS factor that induces the high IL-10 production detected early upon neonatal infection." (PMID 22114550, 2011). "Then, even in the absence of a stabilized Th2 phenotype in response to Trichinella infection, IL-10 would modulate the emerging T helper 1 (Th1) activation during the early phase of infection." (PMID 21429196, 2011). "For the current study on the pathogenesis of PBW we have focused on the single-nucleotide polymorphism (SNP) rs1800872, which is located in the promoter region of the IL10 gene and therefore affects IL-10 production at the site of infection." (PMID 21910858, 2011). "When IP-10 concentration was combined with various other markers of infection such as IL-6, IL-8, and IL-10, the sensitivity and NPV were slightly improved by up to 7%, but the specificity and PPV were dramatically decreased by up to 50%." (PMID 23198120, 2011). "For instance, in analysis of cytokine secretion from endogenous airway memory CD4+ T cells, we found a significant increase in IL-10 expression during secondary infection." (PMID 21647373, 2011). "Although A/J mice succumb to C. albicans infection early after infection (48 h), they mount a similar Th2-like cytokine storm consisting of high levels of IL-6, IL-10 and TNFα, suggesting a common role for C5 in both pathologies." (PMID 22206032, 2011). "Transgenic mice expressing human lactoferrin demonstrated increased IFN-γ and TNF-α, accompanied by decreased IL-10 and IL-5, during infection with Staphylococcus aureus." (PMID 22567270, 2011). "We have recently shown a role for IL-13 and IL-10 in determining disease progression in the murine model of L.(V).panamensis infection." (PMID 21695103, 2011). "Antigen inducible Tregs act to suppress inflammation and prevent tissue and organ injury during responses to infection, mainly by secretion of IL-10 (Tr1) and TGF-β (Th3)." (PMID 21801418, 2011). "The concentration of anti-inflammatory IL-10 was comparable 133 days post-infection but increased in WT mice by day 322 post-infection and remained significantly lower in Tm-TNF mice." (PMID 22132068, 2011).